SCN8A (sodium voltage-gated channel alpha subunit 8)
Diseases named in the same sentence as SCN8A in open-access papers (continued):
Sharing a sentence is not in itself a finding about the gene and the disease.
Epileptic encephalopathy (continued). "On the other hand, gain-of-function mutations in SCN8A can lead to a severe epileptic encephalopathy subtype by over activating NaV1.6 channels." (PMID 32134913, 2020). "One unclassified epileptic encephalopathy patient had two deleterious mutations: SCN8A inherited from his affected father (c.4324G > A, p.E1442K) and IQSEC2 (c.4246_4247insG, p.S1416fs)." (PMID 30185235, 2018). "Early-infantile epileptic encephalopathies (EIEE) caused by SCN8A mutations are designated as EIEE13 (OMIM #614558)." (PMID 30185235, 2018). "Clinical features of six sporadic patients with SCN8A mutations were diverse, ranging from severe epileptic encephalopathy to benign epilepsy with normal cognition." (PMID 28923014, 2017). "SCN2A (Nav1.2) and SCN8A (Nav1.6) mutations are found in patients with early infantile epileptic encephalopathy." (PMID 28536506, 2017). "SCN8A mutation is not only associated with epileptic encephalopathy, but also can be the pathogenic cause of some benign phenotypes, such as BFIS/ICCA, especially the inherited mutations." (PMID 28923014, 2017). "After this publication, various other missense SCN8A mutations in patients with epileptic encephalopathy have been described." (PMID 26252990, 2016). "Approximately 1% of early infantile epileptic encephalopathies are associated with missense mutations in the SCN8A gene, and approximately 50 cases have been described in the literature." (PMID 27900360, 2016). "Mutations of the voltage-gated sodium channel SCN8A have been identified in approximately 1% of nearly 1,500 children with early-infantile epileptic encephalopathies (EIEE) who have been tested by DNA sequencing." (PMID 26029160, 2015). "A second missense mutation, SCN8A-p.Leu1331Val, was identified by targeted resequencing of 65 candidate genes in 500 individuals with epileptic encephalopathy." (PMID 24194747, 2013). "The first de novo mutation in SCN8A was discovered in 2012 by whole genome sequencing of a child with an early onset, debilitating epileptic encephalopathy." (PMID 24194747, 2013). "Using this technology, more than ten mutations of SCN8A have been described during the past year, in patients with epileptic encephalopathy and intellectual disability." (PMID 24194747, 2013). "Overall, this case underscores the diagnostic and therapeutic complexities of managing SCN8A-related epileptic encephalopathy, emphasizing the importance of long-term monitoring and personalized treatment approaches for optimizing outcomes in refractory epilepsy." (PMID 38846250, 2024). "The main diagnosis of children with SCN1A variants was Dravet syndrome (DS) (72.7%), whereas patients with SCN2A and SCN8A variants were mainly diagnosed with various types of epileptic encephalopathy, accounting for 85.7% (12 of 14) and 88.9% (8 of 9) respectively." (PMID 38174099, 2023). "Missense mutations of the SCN8A (sodium voltage-gated channel alpha subunit) gene lead to disruption of the functioning of sodium channels and the development of severe pediatric drug-resistant epileptic encephalopathy." (PMID 38069426, 2023). "SCN8A epileptic encephalopathy is a severe genetic epilepsy with a high risk of SUDEP." (PMID 36160949, 2022). "SCN8A mutations in mice result in ataxia, tremor, and dystonia; in humans, SCN8A haploinsufficiency is associated with intellectual disability, while hyperactivity can contribute to pathogenesis of epileptic encephalopathy." (PMID 34276310, 2021). "Second, in SCN8A, gain-of-function variants lead to epileptic encephalopathy." (PMID 34425903, 2021). "In addition, another de novo mutation of SCN8A was discovered in a child having epileptic encephalopathy with congenital abnormalities." (PMID 33841294, 2021).
Epileptic encephalopathy (continued). "Using parent-offspring trio targeted-exome sequencing, we identified a de novo heterozygous missense mutation c.3953A > G (p.N1318S) in SCN8A in a 3-year-and-9-month Chinese female patient with early infantile epileptic encephalopathy and a normal magnetic resonance imaging of the brain." (PMID 31672125, 2019). "On the basis of electrophysiological analyses using heterologous systems, SCN8A mutations associated with epileptic encephalopathy typically result in alterations such as increased persistent current or slower channel inactivation, which are predicted to increase channel activity." (PMID 29317669, 2018). "Interestingly, mutation of the corresponding leucine residue in SCN1A resulted in impaired channel inactivation, a common feature of SCN8A mutations in epileptic encephalopathy." (PMID 27900360, 2016). "Reported drug response in epileptic encephalopathy due to SCN8A mutations." (PMID 26029160, 2015). "Recurrent de novo mutations of SCN8A in epileptic encephalopathy." (PMID 26029160, 2015). "Functional effects of five SCN8A mutations in patients with epileptic encephalopathy." (PMID 26029160, 2015). "We have generated a mouse model of epileptic encephalopathy carrying the SCN8A-p.Asn1768Asp mutation that may be useful for future evaluation of drug specificity and effectiveness in vivo." (PMID 24194747, 2013). "Additionally, the R850Q mutation in the SCN8A gene has been shown to have a gain-of-function effect, suggesting that it may contribute to the development of early infantile epileptic encephalopathy." (PMID 40565516, 2025). "Theoretically, this approach could benefit individuals with both loss-of-function (protein-truncating variants, missense, splice site) and severe gain-of-function (missense) variants and at least eight cases of epileptic encephalopathy have been identified with variants in 5A of SCN2A or SCN8A." (PMID 34425903, 2021). "Hence, they suggested that a gain-of-function mutation in SCN8A can cause epileptic encephalopathy." (PMID 33841294, 2021). "Taken together, our findings suggest that poison exon usage by Scn1a and Scn8a is a strategy to regulate channel expression during normal brain development, and that mutations recapitulating a fetal-like pattern of splicing cause reduced channel expression and epileptic encephalopathy." (PMID 33411788, 2021). "Thus, mutations in SCN8A account for close to 1% of epileptic encephalopathy." (PMID 26029160, 2015). "Nav1.6 is encoded by the gene SCN8A, gain-of-function mutations of which are associated with epileptic encephalopathy with ataxia." (PMID 37374132, 2023). "Febrile-associated epileptic encephalopathy is a large genetically heterogeneous group that is associated with pathogenic variants in SCN1A, PCDH19, SCN2A, SCN8A, and other genes." (PMID 35711923, 2022). "Stringer and others recently described a patient with epileptic encephalopathy who harbors a de novo heterozygous in-frame duplication in SCN8A (p.G1625_I1627dup) and an inherited heterozygous missense variant in CACNA1H (p.G318S)." (PMID 34867351, 2021). "Recent studies have identified an essential role of the sodium channel Nav1.6, encoded by the gene SCN8A, in epileptic encephalopathy." (PMID 31672125, 2019). "Mutations cause SCN8A epileptic encephalopathy or early infantile epileptic encephalopathy type 13 (OMIM 614558), accounting for ~1% of epileptic encephalopathy cases." (PMID 29121005, 2018). "In SCN8A, the gene related to DEE-13, and cognitive impairment with cerebellar ataxia, we found a missense variant c.5630A>G in Patient 23, who was diagnosed with epileptic encephalopathy, ID, and cerebellar atrophy." (PMID 36674629, 2023). "In this study, we utilize a mouse model of SCN8A epileptic encephalopathy." (PMID 35126041, 2021).
Epileptic encephalopathy (continued). "The recent introduction of exome sequencing in patients with early-onset epileptic encephalopathy resulted in identification of de novo mutation of SCN8A as an important cause of this non-familial disorder." (PMID 26029160, 2015).
Ataxia (39 papers, 2007 to 2025). Ataxia refers to impaired coordination of voluntary muscle movement. "One VUS was concluded to be causal after the discovery of ataxia at the reevaluation by the neurologist and discussions with expert-colleagues in a young patient with a de novo missense variant in SCN8A who grew into the phenotype." (PMID 37889289, 2024). "These implications provide valuable insights for clinicians in diagnosing and managing individuals affected by SCN8A-associated ataxia." (PMID 38251463, 2023). "In our previous large study of SCN8A-associated disorders in ∼400 individuals, ataxia was present in 11/136 individuals with GOF variants, and 5/34 individuals with LOF variants." (PMID 38251463, 2023). "In mice, partial or complete loss-of-function mutations of Scn8a result in motor impairment, symptoms of which also include ataxia." (PMID 37374132, 2023). "Dozens of years after movement disorders had been observed in several spontaneous Scn8a mouse lines (e.g. Scn8a med, Scn8a medj and Scn8a jolting), ataxia as a clinical feature of SCN8A-associated disorders has been recognized." (PMID 38251463, 2023). "In Alpine dachsbracke dogs, ataxia is caused by a mutation in the SCN8A-gene, which encodes a voltage-gated sodium channel and is also associated with ataxia in human." (PMID 35061740, 2022). "Mutations in mouse Nav1.6 have been associated with ataxia, muscle weakness, tremor, dystonia and juvenile lethality, and conditional deletion of Scn8a in mouse cerebellar neurons resulted in mild ataxia." (PMID 31841065, 2020). "Private whole-genome sequence variants of one ataxia case against 600 unrelated controls revealed one protein-changing variant within the critical interval in the SCN8A gene (c.4898G>T; p.Gly1633Val)." (PMID 31083464, 2019). "Pathogenic variants in SCN8A were previously reported in humans with ataxia, pancerebellar atrophy, and cognitive disability." (PMID 31083464, 2019). "A missense mutation in Scn8a is associated with cerebellar ataxia in the so-called ‘jolting’ mutant and is a result of a shift in voltage dependence of the channel opening." (PMID 31083464, 2019). "Protein-changing SCN8A variants have been previously associated with clinically similar movement disorders including cerebellar ataxia, pancerebellar atrophy, and cognitive disability in humans." (PMID 31083464, 2019). "In conclusion, our results provide strong evidence for a breed-specific missense variant in SCN8A gene as the most likely causative genetic variant for monogenic recessive spinocerebellar ataxia in Alpine Dachsbracke dogs." (PMID 31083464, 2019). "In humans, mutations in the gene encoding the NaV1.6 channel (SCN8A), are associated with cerebellar atrophy and ataxia." (PMID 29760657, 2018). "The proband had ataxia and intellectual disability and was found to be heterozygous for a protein truncation mutation of SCN8A." (PMID 26029160, 2015). "Mutations of Scn8a in the mouse result in movement disorders including ataxia, dystonia, and tremor." (PMID 24194747, 2013). "For example, mutations in SCN8A encoding Nav1.6, a major Nav channel subtype expressed at mature nodes of Ranvier, are associated with mental retardation, ataxia, and cerebellar atrophy." (PMID 23834220, 2013). "The reason of that assumption rose form genetic studies which showed that mutations in mice Scn8a gene result in a variety of symptoms ranging from mild ataxia to dystonia, paralysis, and juvenile lethality." (PMID 23409712, 2013). "The role of SCN8A in human disease was initially investigated by screening for mutations in families segregating inherited disorders such as ataxia, dystonia, and tremor." (PMID 24194747, 2013). "Recently, a de novo heterozygous missense mutation in SCN8A was identified in a patient with a severe epileptic encephalopathy consisting of early onset seizures, features of autism, intellectual disability, ataxia, and sudden unexplained death in epilepsy." (PMID 23834220, 2013).
Ataxia (continued). "Our results establish causal evidence for SCN8A-associated episodic and chronic ataxia." (PMID 38251463, 2023). "Ataxia is, therefore, associated with SCN8A mutations in both human and mouse models." (PMID 37374132, 2023). "This is the first report of an SCN8A-associated form of ataxia in dogs." (PMID 31083464, 2019). "Brain sodium channelopathies, which include mutations in SCN1A, SCN2A, SCN3A, and some mutations in SCN8A observed in cases of familial human ataxia and in mice models of ataxia and end-plate diseases (these genes encode the channels NaV1.1, NaV1.2, β1-subunit, and NaV1.6 respectively)." (PMID 22798951, 2012). "In mouse models, mutations in SCN8A lead to ataxia and end-plate disease." (PMID 22798951, 2012). "However, there are biologically interesting genes related to brain volumes including PDE3A, previously related to all aspects of thrombosis, SCN8A linked to cerebellar ataxia with mental retardation, and PDE4B which has been associated with schizophrenia." (PMID 17903297, 2007). "Interestingly, selective removal of SCN8A in Purkinje neurons but not in granule neurons decreased firing rate of Purkinje neurons causing mild ataxia, and double deletion of SCN8A in both Purkinje and granule neurons further decreased Purkinje neuronal firing leading to severe ataxia." (PMID 38251463, 2023). "The first link between human disease and SCN8A mutation was obtained in 2006 in a study of a small pedigree in which heterozygous carriers of a loss-of-function SCN8A mutation exhibited a range of phenotypes including ataxia, cognitive deficits, and emotional instability." (PMID 35557557, 2022). "Electrophysiology on another Scn8a mouse mutant with tremor [Scn8amed−jo/Scn8amed−jo (Ala1071Thr)] showed that the Scn8amed−jo mutation caused a shift in the voltage dependence of SCN8A channel activation, which could decrease neuronal excitability and thus result in ataxia and tremor." (PMID 19737145, 2009). "Care should be taken when our results are used for guiding diagnosis and treatment of SCN8A-related ataxia." (PMID 38251463, 2023). "We set out to investigate disease mechanisms and genotype–phenotype correlations of SCN8A-related ataxia." (PMID 38251463, 2023). "Conditional PC-specific Scn8a knockout mice were previously found to exhibit ataxia, impaired coordination, and deficits in delay eyeblink conditioning and Morris water maze tests which are frequently observed in animal models with autistic features." (PMID 35557557, 2022). "The role of Nav1.6 in human disease was first examined in patients displaying ataxia, dystonia, tremor, and intellectual disability, phenotypes that closely resembled the defects in Scn8a mutant mice." (PMID 34202119, 2021). "While seminal research demonstrated that global knockout of Scn8a in mice was associated with motor impairment and other deficits, a recent conditional knockout of Nav1.6 specifically in peripheral sensory neurons was shown to result in severe ataxia and other motor coordination impairments." (PMID 40830973, 2025). "In our study, we observed only one single case of SCN8A-related ataxia in a continuous series of about 1200 index patients who attended the ataxia clinic in Tübingen since 2012 and received a comprehensive genetic work-up including SCN8A by ataxia gene panel, exome or genome sequencing." (PMID 38251463, 2023). "In contrast, LoF mutations of SCN8A are associated with cognitive deficits and ataxia without seizures." (PMID 29335582, 2018). "Mouse Scn8a (med) mutants exhibit movement disorders including ataxia, tremor and dystonia." (PMID 24194747, 2013). "Due to the broad expression of SCN8A in both excitatory and inhibitory neurons in the brain, these GOF variants may indirectly affect the output of Purkinje neurons through unknown neuronal circuits contributing to ataxia." (PMID 38251463, 2023).
Ataxia (continued). "However, it was not until the mid-2000s that the first human mutation in SCN8A was found in a patient with mental retardation, ataxia and cerebellar atrophy." (PMID 31841065, 2020). "SCN8A has been related with EIEE 13, benign infantile epilepsy, and cerebellar ataxia." (PMID 28923014, 2017). "Non-seizure morbidities are a significant concern in SCN8A-RD, with multiple studies showing high prevalence of symptoms such as communication and developmental delays, hypotonia, ataxia, and autistic-like behavior, as well as feeding, gastrointestinal and sleep difficulties." (PMID 40830973, 2025). "Ataxia as a predominant symptom of SCN8A variation has not been well studied." (PMID 38251463, 2023). "The BCM diagnostic laboratory reported as potentially causal a nonsynonymous variant detected in the SCN8A gene, in which defects cause early infantile epileptic encephalopathy (MIM #614558) and cognitive impairment with or without cerebellar ataxia (MIM #614306)." (PMID 26838676, 2016). "Ataxia-predominant phenotypes, where ataxia is the primary feature and neurodevelopmental abnormalities are mild or absent, and episodic ataxia were not previously considered part of the clinical spectrum of SCN8A-related disorder, and their mechanism was not well-understood." (PMID 38251463, 2023).
Intellectual disability (27 papers, 2013 to 2025). "Patients with SCN8A mutations present with a wide range of clinical features, including mild to severe seizures, developmental delay, intellectual disability, autism, feeding dysfunction, motor impairment, and hypotonia." (PMID 38895634, 2024). "We establish functional evidence for a LoF SCN8A variant by using electrophysiological analyses in a patient with intellectual disability, autism spectrum disorder, and abnormal EEG." (PMID 38233770, 2024). "For example, SCN8A, the mutation of which is a cause of severe intellectual disability and autism, was engaged in RECE and neuron-specific loops whereas its expression level was significantly higher in neurons compared to glia." (PMID 38175672, 2024). "Mutations in Scn8a have been observed in patients with absence epilepsy, intellectual disability, attention-deficit hyperactivity disorder, and autism spectrum disorders." (PMID 37014118, 2023). "De novo missense mutations in SCN8A (encoding Nav1.6) are associated with a spectrum of clinical presentation, including multiple seizure types, movement disorders, intellectual disability, and behavioral abnormalities such as autism." (PMID 35153788, 2022). "All interventions aimed at reducing SCN8A levels would require very careful dosing since SCN8A haploinsufficiency is strongly associated with intellectual disability." (PMID 34425903, 2021). "Four additional de novo missense mutations in SCN8A have been discovered by exome sequencing of patients with intellectual disability." (PMID 24194747, 2013). "The limited functional data suggest that mutations causing increased channel activity are associated with seizures, while heterozygous loss-of-function of SCN8A predisposes to intellectual disability." (PMID 24194747, 2013). "Patients with mutations that alter the function of the sodium channel SCN8A present with a range of clinical features, including mild to severe seizures, developmental delay, intellectual disability, autism, feeding dysfunction, motor impairment, and hypotonia." (PMID 38895634, 2024). "In contrast, loss of function mutations of SCN8A can cause autism or intellectual disability without seizures." (PMID 35557557, 2022).